TLR4 (toll like receptor 4)
Diseases named in the same sentence as TLR4 in open-access papers (continued):
Sharing a sentence is not in itself a finding about the gene and the disease.
food allergy (19 papers, 2009 to 2025). Gastrointestinal disturbances, skin eruptions, or shock due to allergic reactions to allergens in food. "These shrimp allergy-associated genes include HLA-DQ (rs9275596), HLA-DRB1 (HLA-DRB1*04:05-HLA-DQB1*04:01), IL-13 (rs20541, and IL13 rs1800925), and food allergy -associated gene TLR4 rs4986790 (Asp299Gly)." (PMID 39493746, 2024). "The author observed that after killing the intestinal flora of both healthy mice and TLR4-deficient mice with antibiotics, the mice showed food allergy." (PMID 36238281, 2022). "The activation of TLR4-dependent signals inhibits allergic responses to food antigens in experimental animals, and TLR4 knockout mice are highly susceptible to developing food allergies." (PMID 33499808, 2021). "rs4986790 (Asp299Gly) in TLR4 gene associated with children with food allergies." (PMID 39493746, 2024). "However, after antibiotic treatment, gut microbial composition and structure were disturbed in TLR4 wild-type mice, and they were susceptible to the induction of food allergy like the TLR4-mutant mice." (PMID 34335634, 2021). "Neonatal mice reconstituted with TLR4-deficient bone will help to determine whether the increase in TLR4+ cells in the intestinal lamina propria of children with food allergy has physiological relevance." (PMID 30115970, 2018). "Mice susceptible to food allergy have a mutation in TLR4, blocking its signaling." (PMID 23283013, 2009). "Mouse models further illustrate this duality: some studies report that LPS exposure worsens allergic reactions,147,148while others report that TLR4 deficiency (abolishing LPS sensing) exacerbates allergic responses, suggesting that LPS-TLR4 interaction may be involved in food allergy mitigation." (PMID 41328031, 2025). "Other studies employing mouse models found that 2’-FL specifically attenuates β-LG induced food allergy inflammatory symptoms via TLR4/NFκB signaling as 2’-FL itself was shown to reduce expression of key downstream proteins of the TLR4 signaling pathway." (PMID 39877362, 2024). "The produced endotoxin can also stimulate Th1 response through the TLR4 signaling pathway, which can alleviate the occurrence of food allergy." (PMID 37908363, 2023). "TLR4 plays a pivotal role in controlling allergic inflammation, which was found to be significantly increased in Food allergies patients but undetectable in many patients with treated food allergies." (PMID 33499808, 2021). "S100A8/A9 and inflammatory-related factors, including TLR4, NF-κB, TNF-α, IL-6 and IL-1β, is closely related to food allergies." (PMID 33499808, 2021). "In the experimental animal model for food allergy, the gut microbiota and its stimulatory action of innate immune system by toll-like receptors (TLR), particularly TLR4, is of paramount importance." (PMID 23283013, 2009). "In this work, we have synthesized two family of ligands,an 8-oxoadenine derivative as a ligand for TLR7 and a pyrimido[5,4-b]indole as a ligand for TLR4, both conjugated with a T-cellpeptide of Pru p 3 allergen, the lipid transfer protein (LTP) responsiblefor LTP-dependent food allergy." (PMID 34761908, 2021). "The identification of novel processes, such as TLR4-activated myeloid cells in egg allergy or IFN related pathways in baked egg tolerance, prompts further study using traditional experimental approaches that may change our understanding of the immunology of food allergy." (PMID 27788149, 2016). "One LPS-non-responsive animal model is TLR4–/–B6129PF mice, which are in fact prone to develop food allergy." (PMID 32292395, 2020).
lymph node metastasis (19 papers, 2011 to 2025). "Combined high TLR4/MyD88 expression significantly associated with lymph node metastasis (p=0.046) and high-grade tumor budding (p=0.002)." (PMID 40703545, 2025). "TLR4 is associated with lymph node metastasis, and stimulation of TLR4 with LPS has been displayed to accelerate migration and adhesion of esophageal squamous cell carcinoma cells." (PMID 27323819, 2016). "Moreover, the combined results did not change, indicating that our results were stable and reliable, and high expression of TLR4 could predict the risk of lymph node metastasis." (PMID 38463226, 2024). "Combined TLR4/MyD88 scores ≥5 significantly predicted lymph node metastasis (42.9% vs 28.3%, p=0.046) and high-grade tumor budding (p=0.002)." (PMID 40703545, 2025). "Combined TLR4/MyD88 scores ≥5 correlated significantly with lymph node metastasis (42.9% vs 28.3%, p=0.046) and tumor budding grade (p=0.002)." (PMID 40703545, 2025). "This indicated that high expression of TLR4 was significantly correlated with the presence of lymph node metastasis." (PMID 38463226, 2024). "Toll-like receptor 4 (TLR4) protein promotes cervical lymph node metastasis in OSCC by activating the NF-kB pathway, resulting in a poor prognosis." (PMID 36263139, 2022). "Of all the included studies, ten, five, six, eight, four, four and five reported data on TLR4 in lymph node metastasis, tumor size, clinical stage, histologic grade, ER, PR and HER-2 respectively and three studies reported data on the association of TLR4 with survival outcomes." (PMID 38463226, 2024). "A total of 10 studies analyzed the relationship between TLR4 expression and lymph node metastasis." (PMID 38463226, 2024). "Expression of TLR4 or CXCR7 is associated with tumor size and lymph node metastasis." (PMID 24363762, 2013). "Of the 95 lymph node metastases, analyzable samples were available for 70 (TLR1), 72 (TLR2), 77 (TLR4), 58 (TLR5), 76 (TLR6), 72 (TLR7), 76 (TLR8) and 70 (TLR9) cases." (PMID 38709790, 2024). "Our data revealed significant relationships between high TLR4, MD-2 and CXCR7 expression and lymph node metastasis and TNM stage." (PMID 30636642, 2019). "At the same time, the incidence of lymph node metastasis tended to be higher in patients with PTC with high rather than low expression of TLR4 (P < 0.001) or CXCR7 (P < 0.001)." (PMID 24363762, 2013). "Furthermore, we found that combined expression of all three markers (TLR4, MD-2, and CXCR7) more strongly correlated with tumor size, lymph node metastasis and distant metastasis than did each of the three markers alone." (PMID 22180778, 2011). "In addition, the incidence of lymph node metastasis and distant metastasis tended to be higher in patients with PTC with high rather than low expression of TLR4 or CXCR7." (PMID 24363762, 2013).
pertussis (19 papers, 2008 to 2025). A contagious bacterial respiratory infection caused by Bordetella pertussis. "We also show that TLR4-deficient mice have impaired immune responses after immunization with N. meningitidis OMVs and whole cell pertussis vaccine." (PMID 21203418, 2010). "After whole cell pertussis immunization of the TLR4-deficient C3H/HeJ mice, IL-6 and IL-12p70 were almost undetectable in the serum." (PMID 21203418, 2010). "Together, our results demonstrate that whole cell pertussis vaccine immunization induced a Th17/Th1 response, which was impaired in TLR4-deficient mice." (PMID 21203418, 2010). "However, studies to determine the association between TLR4 gene locus and pertussis vaccine immune response are limited to clinical analysis." (PMID 39596635, 2024). "Currently, the evaluation of the acellular pertussis (aP) vaccine depends largely on using different mouse strains, while the TLR4 genotype of different mouse strains in response to pertussis toxin (PT) is not carefully determined." (PMID 39596635, 2024). "Studies have shown that TLR4 can not only bind to lipopolysaccharides but also bind to PT and even have a higher affinity than LPS when the body is immunized with the pertussis vaccine." (PMID 39596635, 2024). "Of all the genes that have been reported to affect the immune response to the pertussis vaccine, the TLR4 gene has been mostly studied in humans." (PMID 39596635, 2024). "The N. meningitidis OMV vaccine and whole cell pertussis vaccine both contain LPS and lipoproteins, which activate TLR4 and TLR2 respectively." (PMID 21203418, 2010). "B. pertussis infection or pertussis vaccination of mice also induced an IL-17 response that was dependent on TLR4 signaling and IL-1, and that contributed to protection against B. pertussis challenge." (PMID 19759900, 2009). "LPS signaling through TLR4 also contributes to Th17 responses in mixed cell culture or after B. pertussis infection and pertussis vaccination." (PMID 19759900, 2009). "We have previously shown a role for Toll-like receptor 4 (Tlr4) in pertussis-infected mice and the pertussis toxin (Ptx)-IgG response in wP-vaccinated children, raising the issue of the relative importance of Tlr4 in wP vaccination of mice." (PMID 18498620, 2008). "Using the DGIdb database, we identified potential drug candidates for three biomarkers: HMOX1 (9 drugs, with Stannsoporfin achieving the highest score), TLR4 (22 drugs, with the pertussis vaccine scoring the highest), and ACE (59 drugs, with cilazapril scoring the highest)." (PMID 40282274, 2025). "Our results indicated that rs13489092, rs13489093, and rs13489097 of TLR4 may affect the antibody level produced by the pertussis vaccine in mice." (PMID 39596635, 2024). "TLR4 adjuvants such as LT-K63r enhance B-cell survival and may enhance long-lived humoral immunity to vaccines like pertussis and tetanus." (PMID 37251388, 2023). "Murine models of pertussis infection show that mice with a functional mutation in the TLR4 gene are more susceptible to infection and a candidate gene approach has indicated that variation in the human TLR-4 gene influences antibody response to pertussis vaccine." (PMID 26231221, 2015). "The involvement of TLR4 in immunity to B. pertussis vaccine has been extensively shown and specific SNPs in the promoter region of the TLR4 gene influencing the antibody response to the pertussis (PT) vaccine have been identified." (PMID 21933421, 2011). "In contrast, others have found that antibody levels are not decreased in TLR4-deficient mice after immunization with whole cell pertussis vaccine." (PMID 21203418, 2010). "We examined whether single nucleotide polymorphisms (SNPs) in genes of the TLR4 pathway and their interaction are associated with the response to whole-cell vaccine (WCV) pertussis vaccination in 490 one-year-old children." (PMID 18987746, 2008).
pertussis (continued). "Previously, researchers have found that the variation in the gene coding for Toll-like receptor 4 (TLR4) is closely related to the infection sensitivity to B.p and vaccine response to the whole-cell pertussis vaccine." (PMID 39596635, 2024). "We also predicted the most effective cores for siRNAs to affect staphylococcus aureus (ClfB, IsdA, sdrC, sdrD, and SasG) and pertussis (PtxE, PagP, PtxD, PtxC, PtxA, and PtxB) bacterial genes that interacted with human KRT10, FGG, and TLR4 genes." (PMID 37169818, 2023). "In this study, five important human genes (KRT10, FGG, TLR4, CD14, and MD2) reported in the development and spread of pertussis and staphylococcus aureus infections." (PMID 37169818, 2023). "Pertussis OMVs with wild-type LPS predominantly activated TLR2 and TLR4 and were more reactogenic than Bexsero." (PMID 37542099, 2023). "Similarly, it has been demonstrated that whole cell pertussis vaccine immunization led to comparable antibody titers in TLR4-deficient and wild type mice, but IFN-γ and IL-17 production of T cells after antigen restimulation was much lower for TLR4-deficient mice." (PMID 21203418, 2010). "Here we investigated the role of TLR2 and TLR4 in the induction of immune responses in mice after immunization with a N. meningitidis OMV vaccine and a whole cell pertussis vaccine." (PMID 21203418, 2010). "It shows that the presence and/or rapid recall of pertussis antibodies are crucial to protection and that TLR9 (better than TLR4 agonists) may improve current aP vaccines and thus possibly better protect adolescents and adults against pertussis." (PMID 31333656, 2019). "Thus it seems that also for whole cell pertussis vaccine, TLR2 or TLR4 activation has little influence on CD4+ T cell proliferation." (PMID 21203418, 2010). "In the present study, we demonstrate that TLR4 signalling by LPS contributes to generation of adaptive immune responses after immunization with N. meningitidis OMVs or whole cell pertussis vaccine, while TLR2 activation was not required." (PMID 21203418, 2010). "However, the pertussis vaccine, while TLR4-related, is not considered relevant for PD or COPD treatment, as its primary function is to induce immunity against Bordetella pertussis, not to modulate chronic inflammation in these diseases." (PMID 41009972, 2025). "However, the genetic background of TLR4 in response to acellular pertussis vaccine challenge has not been carefully evaluated in mice used for vaccine development." (PMID 39596635, 2024). "Sander Banus proved that the rs2770150 locus of the human TLR4 gene may be related to the level of PT-IgG, but there is no research showing the relationship between TLR4 genotyping and pertussis vaccine immune response in mice." (PMID 39596635, 2024). "Furthermore, we observed a significant increase in TLR2 and NOD2, but not TLR4, activation by strains circulating after the introduction of pertussis vaccines." (PMID 28076445, 2017). "Together our data demonstrate that TLR4 activation contributes to the immunogenicity of the N. meningitidis OMV vaccine and the whole cell pertussis vaccine, but that TLR2 activation is not required." (PMID 21203418, 2010). "We conclude that TLR4 activation contributes to the immunogenicity of the N. meningitidis OMV vaccine and the whole cell pertussis vaccine, but that TLR2 activation is not required." (PMID 21203418, 2010). "In contrast, protection induced with acellular pertussis vaccine (ACV), which contains no or limited LPS, was compromised, but not completely abrogated in Tlr4-defective mice." (PMID 18987746, 2008).
thrombosis (19 papers, 2012 to 2025). "Three of all the other four combinations to decrease the activation of Thrombosis included targeting TLR4, while the last one relied on the simultaneous blocking of IL-1β and IL-18." (PMID 36261775, 2022). "The observation that TLR4 activation reverses AA-mediated platelet inhibition under basal conditions may explain the high on-treatment recurrent thrombosis in cats that had experienced CATE." (PMID 41574253, 2025). "In conclusion, TLR4 is involved in venous thrombosis resolution through NF-κB pathway." (PMID 37251076, 2023). "These two TLR4 SNVs are supposed to be protective against thrombosis." (PMID 31040845, 2019). "Although our studies demonstrate that platelet-derived TLR-4 was sufficient to restore LPS-enhanced thrombosis, it remains to be determined whether TLR-4-bearing platelets are exclusively responsible for this effect." (PMID 22911769, 2012). "The release of histones from dying cells is associated with microvascular thrombosis, while blocking platelet TLR2 and TLR4 decreases the percentage of activated platelets and reduces the amount of thrombin generated, indicating that TLR2 and TLR4 mediate the activation process." (PMID 32645848, 2020). "In the present investigation, we found that OP effectively suppressed the activation of TLR4/NF-κB and reduced the levels of inflammatory markers such as TNF-α, IL-1β and IL-6 in liver and lung tissues of mice with carrageenan-induced thrombosis." (PMID 40276603, 2025). "The deep venous thrombosis resolution (DVT) is similar to sterile inflammation, so we hypothesize that TLR4 is involved." (PMID 37251076, 2023). "To investigate the function of the TLR4-IRF3-IFNβ-STAT1α/β axis on venous thrombosis resolution, we evaluated IFNβ and MCP-5 expression by ELISA in Tlr4−/− and WT mice at 1, 3, and 7 subsequent days after IVC ligation." (PMID 37251076, 2023). "Inflammatory mediator toll-like receptor (TLR)-4 plays a critical role in NIH, arterial thrombosis, and stenosis." (PMID 36147190, 2022). "Deep vein thrombosis (DVT) may also be associated with SIBO, especially due to the increased concentration of inflammatory factors and expression of TLR-4 by platelets and endothelial cells." (PMID 36615748, 2022). "TLR-4 can be found on a wide variety of cells including platelets, endothelial cells, and monocytes, however which cells expressing TLR-4 are responsible for the LPS-enhanced microvascular thrombosis remains unclear." (PMID 22911769, 2012).